KRTAP20-3 (keratin associated protein 20-3)
Description:
In the hair cortex, hair keratin intermediate filaments are embedded in an interfilamentous matrix, consisting of hair keratin-associated proteins (KRTAP), which are essential for the formation of a rigid and resistant hair shaft through their extensive disulfide bond cross-linking with abundant cysteine residues of hair keratins. The matrix proteins include the high-sulfur and high-glycine-tyrosine keratins.
Synonyms: KAP20.3; KAP19D; KRTAP19P4
Tractability: No criterion of Open Targets' tractability assessment is met for any kind of drug.
Gene: Protein-coding gene on chromosome 21 (30,642,864 to 30,643,136, forward strand). Ensembl gene ENSG00000206104.
Genetic constraint (gnomAD): Loss-of-function variants: 1 observed, 2.15 expected, observed/expected ratio (o/e) 0.46, 90% interval 0.16 to 1.71. That is too few expected variants to judge how well the gene tolerates losing a copy. Missense variants: 52 observed, 52.85 expected, observed/expected ratio (o/e) 0.98, 90% interval 0.79 to 1.24. Synonymous variants: 16 observed, 21.36 expected, observed/expected ratio (o/e) 0.75, 90% interval 0.51 to 1.14.
Homologues: Orthologues: chimpanzee KRTAP20-3 (100% identical).